YAP1 (Yes1 associated transcriptional regulator)
Diseases named in the same sentence as YAP1 in open-access papers (continued):
Sharing a sentence is not in itself a finding about the gene and the disease.
cancer (continued). "To examine the crosstalk of YAP1 and GLI1, we examined the level of YAP1 protein in cancer cells after the silencing of GLI1." (PMID 34445421, 2021). "The IHC score for YAP1 in the cancer cells of the cancer tissue in the CC group was higher than that in the control group; however, the score in the CC + GL group was lower than that in the CC group." (PMID 33807620, 2021). "YAP1 contributes to cancer invasion and migration by promoting SNAI2 transcription through the transcription cofactor TEAD, in vivo and in vitro assays." (PMID 34446793, 2021). "YAP1 is a crucial transcriptional coactivator in the Hippo pathway and crosstalks with various cancer-promoting pathways." (PMID 35059315, 2021). "As the key component of the Hippo pathway, hyperactivation of YAP1 is widespread in cancers as evidenced from immunostaining of YAP1 in human cancer samples." (PMID 34150758, 2021). "YAP1, primarily as the downstream gene of Hippo signaling pathway, was demonstrated as an important oncogene in a considerable number of cancer types." (PMID 33436041, 2021). "Studies show that YAP1 promotes cell proliferation, metastasis, survival, and stem cell activity, which are critical processes in cancer cells." (PMID 33495421, 2021). "Together, these data show that Hippo inactivation synergizes with mutant RIT1 in cancer models, and Hippo pathway inactivation and YAP1 activation also occurs in RIT1-altered human lung tumors." (PMID 34373451, 2021). "Recent studies also identified YAP1 gene fusion events in several kinds of rare cancers, such as supratentorial (ST) ependymoma, epithelioid hemangioendothelioma, cervical squamous cell carcinoma, endocervical adenocarcinoma, and other cancers." (PMID 34150758, 2021). "Notwithstanding, gene expression data showed that WNT5A and YAP1 expression is moderately-to-strongly correlated in several cancer types." (PMID 33643710, 2021). "Accumulated evidences suggest that nuclear YAP1 plays a crucial role in inhibiting cell senescence in fibroblasts or cancer cells, yet others have demonstrated that hyperactivation of YAP1 can induce cell senescence." (PMID 33495462, 2021). "In this study, we investigate the role of ASAP1-IT1, and the association of ASAP1-IT1, miR-509-3p and YAP1 in NSCLC progression and cancer cell stemness." (PMID 34715859, 2021). "Currently, relatively little is known of the landscape of YAP1 clinical significance in pan-cancers and the identification of featured molecular mechanisms." (PMID 34257617, 2021). "It is worth noticing that the number of cancer samples with SHANK2 amplifications way exceeds those with YAP1 amplification, FAT1 deletion, and NF2 deletion, indicating a previously unnoticed role of SHANK2 as a major oncogene." (PMID 34150758, 2021). "Differences in YAP1 expression between cancer tissues and normal tissues based on the Oncomine database." (PMID 34150844, 2021). "Silencing of MAGI3pPA transcripts and YAP1 activity markedly decreases the growth of MDA-MB-231 cancer cells xenografted in NOD/SCID mice, whereas ectopic expression of the variant promotes anchorage-independent growth of MCF10A-SV40 cells." (PMID 34503076, 2021). "The control of cancer cell growth by YAP1 can be mediated by modulation of the cell cycle, proliferation, and apoptosis." (PMID 33495462, 2021). "YAP1 can induce epithelial-mesenchymal transition, increase the number of cancer stem cells, and inhibit cell apoptosis in vitro, and the abilities of cancer cell invasion, migration, and tumorigenicity in nude mice can be reduced by YAP1 knockdown." (PMID 34691176, 2021). "Various studies highlighted the role of CAFs-induced Yes-activated protein (YAP1), a major regulator of cell plasticity, stemness, drug resistance, and metastasis in carcinoma cells." (PMID 34680267, 2021).
cancer (continued). "Yes-associated protein 1 (YAP1), the transcriptional effector of the Hippo signaling pathway, acts as a potential oncogene in various types of malignant tumors 8-12." (PMID 33123286, 2020). "Currently, VP is the main pharmacological tool to understand the role of YAP1 and a therapeutic alternative for various cancers with a dysregulated Hippo pathway and high nuclear expression of YAP1." (PMID 32218280, 2020). "A previous study utilizing normal and cancerous human prostate tissues and PCa cell lines demonstrated that YAP1 and AR formed a protein complex in the nucleus of cancer cells under androgen-dependent and -independent conditions." (PMID 32293349, 2020). "YAP1 signaling is pivotal for cancer cell proliferation, metastasis and resistance to cell apoptosis." (PMID 32140077, 2020). "Previously, our group has identified the cancer-driving role of YAP1 in GC through its nuclear accumulation." (PMID 32313226, 2020). "Recent studies highlight a critical role of Hippo-YAP1 signalling for the biology of a wide range of cancer types." (PMID 32488048, 2020). "CA3 demonstrated strong inhibitory effects on the growth of OAC, especially on YAP1 overexpressing cancer cells both in vitro and in vivo." (PMID 33665161, 2020). "To enhance the stemness, we further overexpressed YAP1, one of the Hippo pathway transducers, because it was shown to stimulate the stemness and promote malignancy in various types of cancers." (PMID 32977522, 2020). "By the way, YAP1 is a crucial downstream molecule of the Hippo pathway, which involves in the occurrence and development of malignant tumors." (PMID 32918541, 2020). "YAP1 is an essential downstream gene of Hippo pathway and has been reported as a carcinogen in cancers." (PMID 32297697, 2020). "Among the top 10 upregulated gene sets in nlsYAP5SA we found pathways in cancer, cytokine receptor interaction and focal adhesion, in agreement with active YAP1’s capacity to induce cancer and a consequent immune response." (PMID 32404936, 2020). "The rate of mutation in Hippo effectors, YAP1/TAZ, is negligible; however, modifications in their expression patterns is a common phenomenon in several cancer types." (PMID 32722184, 2020). "Our findings on the differential expression, regulation and function of YAP1 protein isoforms provide insight on the role of Hippo/YAP1 signaling in tumorigenesis and targeting of YAP1 for cancer therapy." (PMID 32292505, 2020). "Yes-associated protein 1 (YAP1) and tafazzin (TAZ1) are factors involved in the initiation of cancer development." (PMID 32503307, 2020). "These paradoxical reports remind us that the role of YAP1 in cancer is controversial, and it is crucial to make it clear the relationship between YAP1 expression and its clinical relevance in CRC." (PMID 33240680, 2020). "The present results showed the activation of YAP1 by ALC using an evaluation of ALK-rearranged cancer cells that survived a treatment with ALC." (PMID 31900393, 2020). "In cancers, aberrant activation of YAP1 has been reported by divergent signaling and pathways such as mechanical forces, PI3K, and G protein‐coupled receptor signaling." (PMID 32175692, 2020). "Given that YAP1 and WWTR1 share about 60% homology, it cannot be excluded that we co-detected WWTR1 in addition to YAP1 at least in cancers with very high WWTR1 expression levels." (PMID 32488048, 2020). "In fact, VP has been wildly proposed to downregulate YAP1 in various types of cancers, especially the capability of VP that disrupts the interaction between YAP1 and transcriptional partners." (PMID 32313226, 2020). "Yes-associated protein 1 (YAP1) is a transcriptional effector component of the Hippo pathway, which was involved in the regulation of cancer cell proliferation and apoptosis, especially in gastrointestinal cancer." (PMID 33262782, 2020). "The explicit carcinogenicity of YAP1/TAZ has been observed in various human cancers, and YAP1/TAZ‐induced EMTs have also been reported." (PMID 32678516, 2020).
cancer (continued). "Despite several lines of evidence that supports an oncogenic role for YAP1, the impact of kinases regulating YAP1 activity in cancer is not well understood." (PMID 32404936, 2020). "Here, we evaluated the status of key components of the Hippo pathway in GBC and the effects of targeted inhibition of YAP1 in this cancer." (PMID 32218280, 2020). "The noticeable effect exerted by Hippo pathway dysregulation and constitutive YAP1/TAZ activation on cancer cells supports them as highly attractive therapeutic targets for developing novel therapeutic approaches." (PMID 32154166, 2020). "The transcriptional co-activator Yes-associated protein 1 (YAP1) is known to regulate the expression of target genes involved in the interactions between the extracellular matrix and cancer cells, and plays an important role in cellular invasion." (PMID 33375621, 2020). "Surprisingly, this study sheds light on the possible integration of IL-13/STAT6 axis and Hippo signaling through YAP1 in cancer progression in NASH." (PMID 32283835, 2020). "YAP1, a transcriptional co-activator that functions in the Hippo signaling pathway, is involved in the initiation and development of several cancers including PTC." (PMID 33197895, 2020). "Due to limited knowledge of YAP1 upregulation in cancer, it is a great challenge of therapeutic targets toward the Hippo–YAP1 pathway." (PMID 33489890, 2020). "Oppositely, the overexpression of Yap1 can convert differentiated cancer cells of the liver into CSCs." (PMID 32932969, 2020). "Differential hydroxymethylation is found in thousands of genes, most significantly in genes related to pancreas development or function (GATA4, GATA6, PROX1, ONECUT1, MEIS2), and cancer pathogenesis (YAP1, TEAD1, PROX1, IGF1)." (PMID 33077732, 2020). "We propose that the TLK1>NEK1>YAP1 axis is a key determinant for cancer progression, particularly during the process of androgen-sensitive to -independent conversion during progression to mCRPC." (PMID 33297404, 2020). "Overall, these data suggest NEK1 increases YAP1 level by reducing YAP1 protein turnover rate in different cancers." (PMID 33297404, 2020). "Accordingly, enhanced expression and nuclear localization of Yap1/Taz were observed in multiple human cancers and inactivation of upstream Hippo signaling leads to tumor formation." (PMID 31958058, 2020). "Specifically, NUSAP1 exerts cancer-promoting functions in GC cells, and these effects are partially reversed by YAP1 depletion." (PMID 33489890, 2020). "Specifically, high nuclear and cytoplasmic YAP1 immunoscores were detected in 70.7% (169/239) and 63.1% (125/216) of advanced cancers and 91.5% (65/71) and 100% (71/71) of CC samples, respectively." (PMID 32218280, 2020). "Upregulation of YAP1 expression and its nuclear translocation are frequently detected in several human cancers, including breast cancer, hepatocellular carcinoma, and GC." (PMID 33489890, 2020). "After initial evaluation of the biological effects of YAP1 inhibition via siRNA pool on GBC cell lines, we studied the in vitro effects of VP, a known suppressor of YAP1-TEAD complex with great potential to be used in cancer therapy." (PMID 32218280, 2020). "For further mining important driving factors for cancers, we explored the network of Kinases, miRNA and TF potentially responsible for YAP1 dysregulation." (PMID 33123286, 2020). "Consistent with the fact that FSTL5 mutations are often accompanied by YAP1 activation, the combination of XPO1 inhibitor and VP significantly inhibited the proliferation of these resistant KRAS/FSTL5 double mutant cancer cells." (PMID 33178014, 2020). "YAP1 has also been shown to be required for KRAS and ST-mediated transformation, providing further evidence that YAP1 is critical for cancer development and maintenance." (PMID 31913126, 2020).
cancer (continued). "Using a Venn diagram, we found 15 genes that were predicted by the three databases; of these, we focused on YAP1, a gene that has been reported as involved in carcinoma development, including GC." (PMID 33262782, 2020). "YAP1 was reported to be amplified and overexpressed in many cancers, and patients were suggested to receive further treatment, such as chemotherapy and hepatectomy." (PMID 31613226, 2019). "Our previous study indicated that silencing of both ERK1 and ERK2 decreased YAP1 expression in cancer cells." (PMID 31848326, 2019). "Platelets promote cancer metastasis also depending on the activating of YAP1 signaling through the RhoA / MYPT-PP1 pathway." (PMID 30646853, 2019). "In recent years, an increasing number of studies have been published which explored the correlation between YAP1 and patient prognosis with cancers." (PMID 31613226, 2019). "Thirdly, having benefited from more studies, our study further explored the prognostic value of YAP1 expression in different specific cancers." (PMID 31613226, 2019). "Activated LATS1/2 further phosphorylates Yes-associated protein 1 (YAP1) and WW domain that contain transcription regulator 1 (TAZ), which are two oncogenic paralogs related to cancer initiation and development." (PMID 30934860, 2019). "Mechanical activation of YAP1 leads to uncontrollable growth and metastatic phenotypes of cancer cells." (PMID 30934860, 2019). "This resistance accounts for difficulties in the management of numerous cancers, due to either cellular adaptation to stress or an increase in anti-apoptotic proteins, such as the YAP-1 transcriptional target inhibitor of apoptosis protein (IAP)." (PMID 31766357, 2019). "In this study, we gathered more studies to assess the prognostic value of YAP1 overexpression in patients with cancer." (PMID 31613226, 2019). "Multiple cancer types are characterized by accumulation of nuclear Yap1, which is prevalent in highly proliferative, aggressive tumors and is associated with poor outcomes." (PMID 30956771, 2019). "Most components of the Hippo pathway, especially the key downstream effector YAP1, has vital function in various human cancers." (PMID 31455378, 2019). "Fourthly, we tried our best to illustrate the potential mechanism of YAP1 functioned in cancer development through subgroup analysis of YAP1 staining location." (PMID 31613226, 2019). "Currently, VP has been widely used to understand the role of YAP1 in various cancers and is used for the treatment of various cancers." (PMID 30846786, 2019). "The data with verteporfin should be interpreted with some caution since there is a report of YAP1 independent effects of the drug in cancer cells." (PMID 31883523, 2019). "Soluble factor Amphiregulin binds EGFR and acts as an autocrine growth factor for establishing a positive autocrine regulatory feedback loop between EGFR and YAP1, which is important in cancer progression." (PMID 30805310, 2019). "Previously, we discovered a crosstalk between the MAPK/ERK pathway and YAP1 signaling in cancer cells." (PMID 31848326, 2019). "The role of the Hippo/YAP1 signaling pathway in cancer development has been intensively studied over the past 10 years." (PMID 30840887, 2019). "Previous reports identified several non-coding RNAs as the regulator of YAP1 mRNA expression in cancer cells." (PMID 31848326, 2019). "ZEB1 is known as a transcriptional repressor of epithelial genes; however, a recent paper by Lehmann has reported that ZEB1 switches its function to a transcriptional co-activator by interacting with YAP1 in aggressive cancers." (PMID 30909436, 2019). "Next, we investigated the role of YAP1 in DGUOK‐mediated cancer cell stemness by ectopically expressing YAP1‐6SA, a constitutively active mutant of YAP1, in control and DGUOK KO cells." (PMID 31633874, 2019).
cancer (continued). "In this review, we have discussed some of the potential mechanisms for targeting CSCs, the therapeutic challenges presented in various cancers, and the development of YAP1-targeting strategies." (PMID 31137841, 2019). "This screening system identified 25 genes correlated with YAP1 expression in the cancer group, among which we selected NMU as the most significantly overexpressed gene in patient samples and cancer cell lines." (PMID 31575084, 2019). "Given the significant role of LIF/YAP1-focal adhesion signaling in cancer dissemination, targeting of this pathway presents a promising opportunity to block metastasis." (PMID 30504771, 2018). "Next, we tested if YAP1/TAZ were indeed bonafide downstream targets of the β1-integrin-FAK signaling by treating cancer cells with a FAK inhibitor, PF-228, to inhibit auto-phosphorylation of Tyrosine 397 of this kinase." (PMID 29872721, 2018). "Based on this report, VP has been used as a pharmacological tool to study the protumorigenic activity of YAP1 in several cancer models." (PMID 30263014, 2018). "In agreement with these, preclinical studies with two experimental liver metastasis mouse models demonstrate that VASP knockdown suppresses GI cancer liver metastasis, β1-integrin activation, and YAP1/TAZ levels of metastatic cancer cells." (PMID 29872721, 2018). "The overlap was 15 of the up-regulated and 2 of the down-regulated genes, suggesting that YAP1 S127 and KRAS G12V up-regulated mitosis and cell cycle-associated genes whose high expression is associated with poor survival pan-cancer." (PMID 30353028, 2018). "Yap1 is a Hippo pathway transcriptional effector that plays numerous roles in development and cancer." (PMID 30561326, 2018). "In glioblastoma, phosphorylation of AMOTL2 by the mTORC2 kinase enhances YAP1 signaling, leading to cancer growth and invasiveness." (PMID 29650031, 2018). "Higher cytoplasmic LIF enhances cancer vascular dissemination and local invasion mechanistically through modulation of YAP1-FAK/PXN signaling." (PMID 30504771, 2018). "To begin addressing FAT1 functions in cancer, we focused on HNSCC, the cancer type in which FAT1 is most frequently mutated and which displays characteristic Hippo signaling dependency, YAP1 overactivity, and frequent YAP1 gene amplification." (PMID 29985391, 2018). "In the current study, we investigated the mechanisms underlying the LIF-mediated cancer metastasis and provide evidence linking LIF with cancer dissemination by driving invadopodia formation and modulation of the YAP1-FAK/PXN pathway." (PMID 30504771, 2018). "From a clinical perspective, AZD0530 treatment presents an ideal strategy to disrupt the metastatic process in cancers associated with LIF, LIFR, or YAP1 activation." (PMID 30504771, 2018). "A Zeb1lo, CD44lo, E-Cadherin+, Zeb2−, Pten−, pS473Akt+, Bmi1+, nuclear Yap1+ pattern was maintained in cancer cells as they divided symmetrically to form papillary tumors." (PMID 29930325, 2018). "The negative correlation between reduced YAP1 expression and metastasis is supported by the observation that depletion of YAP1 in WT or LIF-low cancer cells resulted in a phenotype resembling LIF-rich cancer cells." (PMID 30504771, 2018). "Several other distinct small molecules, including dasatinib, pazopanib, and ivermectin, have also been identified to inhibit YAP1/TAZ by drug screening using human cancer cell lines." (PMID 29565815, 2018). "Pharmaceutical intervention with AZD0530 markedly reverses LIF-mediated cancer dissemination and local invasion through promotion of cytoplasmic accumulation of YAP1 and suppression of focal adhesion kinases." (PMID 30504771, 2018). "In conclusion, the independent impact of YAP1 activation on patients’ survival was repeatedly proven by several independent studies and in a large variety of human cancers." (PMID 30006603, 2018). "Above all, the key co‐effectors YAP1/TAZ are responsible for various key attributes of many different human cancers." (PMID 28782275, 2018).